CLDN6 (claudin 6)
Diseases named in the same sentence as CLDN6 in open-access papers (continued):
Sharing a sentence is not in itself a finding about the gene and the disease.
breast carcinoma (continued). "β-catenin was repressed by CLDN6, even under normal oxygen conditions, which may explain why CLDN6 inhibits the invasion and migration of breast cancer cells under both normoxic and hypoxic conditions." (PMID 32093760, 2020). "In contrast to breast cancer, claudin-6 in endometrial cancer possesses a different function." (PMID 32197343, 2020). "Thus, we propose that CLDN6 plays an anti-metastatic role in breast cancer by antagonizing the SENP1/HIF-1α signalling pathway." (PMID 32093760, 2020). "Because K391 and K477 SUMO sites are required for SENP1-regulated HIF-1α deSUMOylation, we wondered whether mutations in the SUMO site in HIF-1α would prevent the effect of CLDN6 overexpression in breast cancer cells." (PMID 32093760, 2020). "Furthermore, the inhibitory effects of ERβ on the migration and invasion of breast cancer cells were mediated through CLDN6-induced autophagy." (PMID 31412908, 2019). "Therefore, we believe that the regulation of CLDN6 by ERβ is a ligand-dependent pathway in breast cancer cells." (PMID 31412908, 2019). "Our previous study demonstrated that CLDN6 is a breast cancer suppressor gene." (PMID 31412908, 2019). "Interestingly, Afadin has been demonstrated recently to interact with Claudin-6 in MDA-MB-231 breast cancer cells." (PMID 30692208, 2019). "High expression of CLDN6 confers chemoresistance on breast cancer." (PMID 30910845, 2019). "However, CLDN6 expression in breast cancer cells overexpressing ERβ was increased after DPN treatment." (PMID 31412908, 2019). "The effect of DPN on CLDN6 was similar to that of E2 in breast cancer cells." (PMID 31412908, 2019). "Moreover, in our recent studies, we found that CLDN6 overexpression not only strengthened the tight junctions in breast cancer cells but also induced a large number of autophagic vacuoles observed under transmission electron microscopy (TEM)." (PMID 31412908, 2019). "Hence, the current study aimed to explore the regulatory role of ERβ on CLDN6 expression in breast cancer cells and the mechanism related to its biological functions." (PMID 31412908, 2019). "ERβ inhibited the migration and invasion of breast cancer cells through CLDN6." (PMID 31412908, 2019). "Since we have previously demonstrated that CLDN6 overexpression led to a lower migration and invasion of breast cancer cells, we investigated whether E2-induced CLDN6 expression was involved in reducing breast cancer cell migration and invasion." (PMID 31412908, 2019). "Finally, we analyzed the correlation between GSTP1 and CLDN6 expression in 40 human breast cancer tissues by using immunohistochemistry." (PMID 29116019, 2017). "We therefore hypothesized that CLDN6 may also play a role in conferring chemoresistance on breast cancer cells." (PMID 29116019, 2017). "Besides, we have found that CLDN6 function as a tumor suppressor in breast cancer cells, inhibiting the malignant phenotype of breast cancer cells, such as growth, migration, and invasion via p38/MAPK pathway." (PMID 29116019, 2017). "Abnormal high CLDN6 expression was found in MCF-7/MDR multidrug resistant breast cancer cells, however whether CLDN6 confers resistance to various anti-cancer drugs in this cell line need to be explored." (PMID 29116019, 2017). "We then overexpressed CLDN6 in MCF-7 cells to determine whether CLDN6 affects chemoresistance in breast cancer cells." (PMID 29116019, 2017). "And we also reported that CLDN6 induced human breast cancer cells apoptosis via ASK1 signaling." (PMID 29116019, 2017). "However, we also found that CLDN6 was highly expressed in multidrug resistant breast cancer cell line MCF-7/MDR that derived from human MCF-7 cell line." (PMID 29116019, 2017).
breast carcinoma (continued). "The downregulation of tight junction protein CLDN6 promotes breast cancer cell migration and invasion; however, the exact mechanism underlying CLDN6 downregulation remains unclear." (PMID 28867761, 2017). "To test whether CLDN6 affects chemoresistance in breast cancer cells, we utilized RNAi to transiently or stalely inhibit CLDN6 expression in MCF-7/MDR cells and we found that expression of P-gp also decreased simultaneously." (PMID 29116019, 2017). "CLDN6 expression is related to DNA methylation in breast cancer tissues and MCF-7 cells." (PMID 27461117, 2016). "Down-regulation of CLDN6 expression could facilitate migratory and invasive phenotype in breast cancer cells." (PMID 27461117, 2016). "Besides, tissues derived from breast carcinoma with lymph node metastasis were also accompanied with decreasing expression of CLDN6." (PMID 27461117, 2016). "Then we hypothesized that the low expression of CLDN6 might be correlated with DNA methylation in breast cancer." (PMID 27461117, 2016). "To evaluate whether demethylation of CLDN6 plays a role in breast cancer progression, we analyzed invasive and migratory abilities in MCF-7 cells treated with 5-aza-dC." (PMID 27461117, 2016). "In our previous work, we have identified CLDN6 as a potential mammary cancer suppressor gene, which may contribute to mammary cancer resistant phenotype observed in human and rat mammary cancer cell lines." (PMID 27461117, 2016). "Therefore, the purpose of the current study is to discover the relationship between ASK1 and claudin-6 in breast cancer and to explore the pathways involves the activation of ASK1." (PMID 22925655, 2012). "Besides analysis of the breast cancer tissues, we also analyzed the correlation of ASK1 and claudin-6 mRNA and protein in breast cancer cell lines." (PMID 22925655, 2012). "We have previously investigated the possibility that the expression of claudin-6 was negatively correlated with the hypermethylation promoter of claudin-6 in breast cancer tissues (data unpublished), suggesting that the down-regulation of claudin-6 is associated with its DNA methylation." (PMID 22455563, 2012). "Our data suggests, for the first time, that the ASK1 signal may play a positive role in the inhibitory effect of claudin-6 in breast cancer." (PMID 22925655, 2012). "However, the exact mechanism by which CLDN6 triggers ferroptosis is still elusive in breast cancer." (PMID 39984471, 2025). "Therefore, we hypothesized that chemotherapy may upregulate CLDN6 expression in breast cancer cells through the ROS/GATA4 axis." (PMID 40959289, 2025). "Furthermore, CLDN6 has been shown to mediate the anti-migratory and anti-invasive effects of estrogen receptor β (ERβ) by triggering a Beclin1-dependent autophagic cascade, linking tight junction regulation to autophagy in breast cancer suppression." (PMID 40687428, 2025). "Moreover, WIP knockdown reversed the inhibitory effect of CLDN6 on breast cancer metastasis." (PMID 36935496, 2023). "Moreover, we observed that WIP colocalized with LC3 in CLDN6-overexpressing breast cancer cells." (PMID 36935496, 2023). "We then evaluated whether WIP was critical for CLDN6-mediated autophagy in breast cancer cells." (PMID 36935496, 2023). "In the human breast cancer cell MCF-7, for clones transfected with CLDN6, the level of apoptosis signal-regulating kinase 1 (ASK1) protein and mRNA was up-regulated, which indicates that the ASK1 signal may be associated with the pro-apoptosis effect of CLDN6." (PMID 36362009, 2022). "However, the mechanism by which CLDN6 inhibits breast cancer proliferation is unclear." (PMID 35008557, 2021). "Hence, we assumed that CLDN6 suppressed aerobic glycolysis of breast cancer cells." (PMID 35008557, 2021). "However, we have found the proliferation of MCF–7 breast cancer cells was suppressed upon CLDN6 overexpression, but the mechanism was unknown." (PMID 35008557, 2021).
breast carcinoma (continued). "However, over-expression of CLDN6 may suppress the progression of breast cancer, whereas DNA methylation of CLDN6 can downregulate its gene expression and promote migration and invasion." (PMID 34409042, 2021). "However, HIF-1α promotes CLDN6 transcription in hypoxic cultured breast cancer cells." (PMID 34948213, 2021). "However, the ability of CLDN6 as a prognostic marker for breast cancer remains to be discussed, as our findings suggest that there seems no clinicopathological correlation of CLDN6 expression in human breast cancers." (PMID 32093760, 2020). "ERβ agonists and CLDN6 may be novel therapeutic approaches for the treatment of breast cancer." (PMID 31412908, 2019). "In addition, CLDN6 expression was inversely correlated with breast cancer cell metastasis, indicating that CLDN6 might play an important role in suppressing breast cancer progression." (PMID 27461117, 2016). "Importantly, mRNA levels of the tumor suppressor gene claudin-6 (CLDN6) reported to be increased in breast cancer cells upon DAC treatment were induced in all cell types regardless of their subtype classification, while GAPDH mRNA, a house keeping gene did not change following DAC treatment." (PMID 25860442, 2015). "In a previous study, we showed that the protein and gene expression of claudin-6 was low or undetectable in human and rat mammary cancer cell lines, and the cell growth, migration and invasion were inhibited by overexpression of claudin-6 in breast cancer MCF-7 cells." (PMID 22455563, 2012). "In this study, we confirmed the prognostic significance of integrating CLDN6 with ferroptosis, and elucidated a novel mechanism by which CLDN6 triggers NRF2-mediated ferroptosis in breast cancer." (PMID 39984471, 2025). "The expression levels and clinical implication of CLDN6, WIP and LC3 in breast cancer tissues were evaluated using immunohistochemistry." (PMID 36935496, 2023). "To validate the relationship between CLDN6, WIP and LC3 expression and metastasis in breast cancer patients, we analyzed their mRNA expression with the GEO database." (PMID 36935496, 2023). "We also found that c-Jun phosphorylation was upregulated in CLDN6-overexpressing breast cancer cells, and c-Jun knockdown eliminated the promotion of WIP induced by CLDN6 overexpression." (PMID 36935496, 2023). "In breast cancer cells such as MCF-7, CLDN6 expression confers cellular resistance to drugs such as 5-fluouracil (5-FU) and adriamycin." (PMID 38137355, 2023). "Pearson correlation analyses indicated that CLDN6 was positively correlated with WIP and LC3, and that WIP was positively correlated with LC3 in breast cancer tissues." (PMID 36935496, 2023). "Using lentivirus transduction, we constructed breast cancer MCF-7 and MDA-MB-231 cell lines with stable overexpression of CLDN6." (PMID 36935496, 2023). "CLDN6, a member of claudin (CLDN) family, was found to be a breast cancer suppressor gene in our early experiments." (PMID 34405008, 2021). "To verify the low expression of CLDN6 in breast cancer tissues, we analyzed the mRNA expression of CLDN6 with the GEO database GSE134359, which showed that the level of CLDN6 mRNA in breast tumor tissues was lower than that in normal tissues." (PMID 35008557, 2021). "For example, CLDN6 combines with PDZ-containing protein ZO-1, and then ZO-1, UVRAG, and BECLIN1 form complexes to regulate autophagosome formation in breast cancer cells." (PMID 34948213, 2021). "To evaluate the relationship between CLDN6/TAZ/c–MYC expression and clinicopathological parameters, we did a TMA–IHC analysis of breast cancer patients." (PMID 35008557, 2021).
breast carcinoma (continued). "Knockdown of CLDN6 reduced the expression and the enzyme activity of GSTP1 and increased the cytotoxicity of adriamycin, 5-FU, and cisplatin in ER+ breast cancer cells." (PMID 33946704, 2021). "However, our recent work has shown that CLDN6 may be a tumour suppressor gene in breast cancer." (PMID 32093760, 2020). "A Pearson correlation analysis demonstrated that CLDN6 expression was negatively correlated with SENP1 and HIF-1α in breast cancer tissues." (PMID 32093760, 2020). "Considering the distinct function of CLDN6 and HIF-1α in tumour metastasis, we chose a breast cancer cell line with strong invasion, MDA-MB-231, and a breast cancer cell line with weaker invasion, SkBr-3, for the following experiments." (PMID 32093760, 2020). "Gene expression data from a breast cancer microarray were acquired from the GEO database (GSE27562), and a GSEA was performed for SENP1 and CLDN6 expression." (PMID 32093760, 2020). "Compared with breast cancer cell lines, HBL-100 cells express more CLDN6, and knocking down the expression of CLDN6 can promote interstitial-like transformation of HBL-100 cells." (PMID 32093760, 2020). "In previous studies, our group first cloned the CLDN6 gene from mammary epithelial cells of COP rats and identified CLDN6 as a breast cancer suppressor gene." (PMID 31412908, 2019). "Inactivation of the TGFβ/SMAD pathway has been shown to inhibit cell invasion by suppressing DNMT1 and claudin-6 methylation and expression in MCF-7 and SKBR-3 breast cancer cell lines." (PMID 31717460, 2019). "In conclusion, SMAD2 downregulated CLDN6 via DNMT1 mediated DNA methylation to promote EMT, thereby accelerating the migration and invasion of breast cancer cells." (PMID 28867761, 2017). "Claudin-6 (CLDN6), a member of CLDN family and a key component of tight junction, has been reported to function as a tumor suppressor in breast cancer." (PMID 29116019, 2017). "However, whether CLDN6 plays any role in breast cancer chemoresistance remains unclear." (PMID 29116019, 2017). "In our study we firstly examined CLDN6 expression and methylation status at CLDN6 gene CpG sites in breast cancer tissues and MCF-7 cells to study relationship between CLDN6 expression and DNA methylation." (PMID 27461117, 2016). "As a conclusion, our study suggests that the ASK1 expression is low in breast cancer, and the levels of ASK1 mRNA and protein expression are correlated with that of claudin-6." (PMID 22925655, 2012). "Prior to this study, our group had cloned the CLDN6 gene from mammary epithelial cells of COP rats for the first time and found that CLDN6 exerted tumor suppressive function while its expression was low in breast cancer." (PMID 39984471, 2025). "To determine whether the effects of CLDN6 on ferroptosis were dependent on NRF2, we overexpressed NRF2 in CLDN6-overexpressing breast cancer cells and detected NRF2 target genes." (PMID 39984471, 2025). "For example, SUMOylation‐dependent HIF‐1α/CLDN6 negative feedback contributes to the metastasis of breast cancer." (PMID 40954549, 2025). "Nonetheless, there have been no studies that integrate CLDN6 and ferroptosis to predict prognosis, and the impact of CLDN6 on ferroptosis is still elusive in breast cancer." (PMID 39984471, 2025). "Our study is the first to uncover a positive feedback loop of CLDN6 and JNK/c-Jun signaling, which may increase the inhibitory effect of CLDN6 on breast cancer metastasis." (PMID 36935496, 2023). "Finally, we investigated the correlation between CLDN6, WIP and LC3 expression in breast cancer tissues and the relationship between them and clinicopathological characteristics of breast cancer patients." (PMID 36935496, 2023). "HIF-1α accumulation under hypoxia might promote CLDN6 transcription, and increased CLDN6 would weaken HIF-1α protein stability and slow down hypoxia-induced breast cancer metastasis." (PMID 35847894, 2022).
breast carcinoma (continued). "Therefore, silencing CLDN6 suppressed EMT, and subsequently inhibited the migration and invasion of breast cancer cells." (PMID 34405008, 2021). "In our study, CLDN6 appears to be able to regulate the HIF-1 pathway through SENP1 not only in breast cancer cell lines but also in non-tumorigenic HBL-100 cell lines." (PMID 32093760, 2020). "Claudin-6 (CLDN6), a tight junction protein, acts as a tumor suppressor gene in breast cancer." (PMID 31412908, 2019). "When ERβ was knocked down in breast cancer cells, the expression of CLDN6 was not increased after DPN treatment." (PMID 31412908, 2019). "Finally, immunohistochemistry was used to explore the relationship between CLDN6 and GSTP1 expression in breast cancer tissues." (PMID 29116019, 2017). "After treating the two breast cancer cell lines with SB431542, a TGFβ type I receptor inhibitor that specifically inhibits SMAD2 and SMAD3 phosphorylation, which leads to down regulation of DNMT1 and upregulation of CLDN6." (PMID 28867761, 2017). "Therefore, inactivation of SMAD2 upregulated CLDN6 suppressed EMT, and subsequently inhibited the migration and invasion of breast cancer cells." (PMID 28867761, 2017). "Thus, CLDN6 is the key regulator in the SMAD2/DNMT1/CLDN6 pathway to inhibit EMT and migration and invasion of breast cancer cells." (PMID 28867761, 2017). "Despite several reports describing claudin-6 expression in multiple human cancers such as rhabdoid tumors, breast cancer and gastric cancer, the function of claudin-6 in cancer cells has not been analyzed in detail." (PMID 24009024, 2013). "We recently found claudin-6 inhibited invasion in breast cancer cells by reversing EMT (data not show)." (PMID 24245968, 2013). "We have identified a novel mechanism responsible for the pro-apoptosis function of claudin-6, and ASK1 may become a target for breast cancer treatments." (PMID 22925655, 2012). "Claudin-6 expression is inactivated by aberrant CpG island DNA hypermethylation in its promoter region in the breast cancer cell MCF-7, suggesting that DNA methylation may have an important role in regulation of claudin-6 expression in breast cancer." (PMID 22455563, 2012). "We found the correlation between claudin-6 and ASK1 expression in breast invasive ductal carcinomas tissues, but their relationship in breast cancer cell line was unknown." (PMID 22925655, 2012). "Thus, we speculated that CLDN6 may regulate WIP to affect actin cytoskeleton during autophagy, and further inhibit breast cancer metastasis." (PMID 36935496, 2023). "Therefore, WIP inhibited breast cancer metastasis through autophagy, not through pseudopodia in CLDN6-overexpressing breast cancer cells." (PMID 36935496, 2023). "Interestingly, the nuclear receptor estrogen receptor β (ERβ), which is considered a tumor suppressor in breast cancer, induces Claudin-6 (CLDN6)-mediated autophagic activity via directly transactivating CLDN6, thereby inhibiting the migration and invasion in breast cancer." (PMID 34207792, 2021). "We found that the level of CLDN6 in MCF-7/MDR cells was higher compared to MCF-7 cells, suggesting that CLDN6 may be a key element in conferring multidrug resistance of breast cancer." (PMID 29116019, 2017). "Furthermore, in breast cancer cell lines (MDA-MB-231 cells), miR-7 and miR-218 resulted in an increase of cells at the G1 phase and a decrease of cells at the S phase with reactivation of CLDN6 by means of epigenetic switches in DNA methylation and histone modification." (PMID 36362009, 2022).